OR1D4 (olfactory receptor family 1 subfamily D member 4)
Description:
Odorant receptor.
Synonyms: OR17-30
Gene: Transcribed unprocessed pseudogene on chromosome 17 (3,240,676 to 3,241,614, forward strand). Ensembl gene ENSG00000255095.
Subcellular location: Cell membrane
Pathways (Reactome):
Sensory Perception: Expression and translocation of olfactory receptors
Diseases named in the same sentence as OR1D4 in open-access papers:
OR1D4 is named in the same sentence as 2 diseases in open-access papers, as found by Europe PMC text mining. Sharing a sentence is not in itself a finding about the gene and the disease. The quoted sentences say what the papers report.
breast carcinoma (1 paper, 2020). "Likewise, many were upregulated by recurrent downstream fusions (geneDIB), including SIX2 in thyroid and CHI3L1 and OR1D4 in breast cancers." (PMID 32631391, 2020).
thyroid cancer (1 paper, 2020). "We detect a number of recurrent fusions, such as those involving ANO3, RGS9, FUT5, CHI3L1, OR1D4, and LIPG in breast; IGF2 in colon; ETV1 in prostate; and IGF2BP3 and SIX2 in thyroid cancers." (PMID 32631391, 2020).